PEG10 (paternally expressed 10)
Diseases named in the same sentence as PEG10 in open-access papers:
PEG10 is named in the same sentence as 54 diseases in open-access papers, as found by Europe PMC text mining. Sharing a sentence is not in itself a finding about the gene and the disease. The quoted sentences say what the papers report.
hepatocellular carcinoma (12 papers, 2012 to 2022). A malignant tumor that arises from hepatocytes. "PEG10 expression has been linked to worse prognosis and tumor progression or recurrence in endometrial cancer, hepatocellular carcinoma, oral squamous cell carcinoma, showing potential predictive and prognostic ability as a biomarker." (PMID 35677557, 2022). "Among them, PEG10 is a known paternally imprinted gene in both human and pig, and this gene has been reported to be associated with several malignancies, such as hepatocellular carcinoma and B-cell lymphocytic leukemia in human." (PMID 31208168, 2019). "PEG10 was a famous oncogene and a downstream target of miRNA-27a-3p and miRNA-34a-5p in hepatocellular carcinoma, as well as, PEG10 regulated endometrial cancer and bladder cancer." (PMID 36385135, 2022). "A recent study suggested that TSG101 promotes the proliferation, migration, and invasion of hepatocellular carcinoma cells by regulating the expression of PEG10 (paternally expressed 10) gene." (PMID 30759747, 2019). "PEG10 is a postulated target of 7q21 amplification in hepatocellular carcinoma and its overexpression in cancer correlates with disease progression, invasiveness and aggressiveness." (PMID 25057852, 2014). "However, PEG10 dysregulation was reported in multiple tumours, such as metastasis prostate tumours, hepatocellular carcinoma, and endometrial cancer." (PMID 34775482, 2021). "Overexpression of PEG10 may be involved in the invasion and metastasis of malignant tumors, such as hepatocellular carcinoma and endometrial cancer etc., through the epithelial mesenchymal transition (EMT)." (PMID 33407475, 2021). "Interestingly, PEG10 is a biomarker for progressive development and invasion of hepatocellular carcinoma, gallbladder adenocarcinoma and acute lymphoid leukemia and is found to be regulated by androgens." (PMID 22295114, 2012). "The overexpression of the PEG10 gene has also been detected in human cancers, including leukemia, breast cancer, hepatocellular carcinoma (HCC), prostate cancer and pancreatic cancer." (PMID 24944680, 2014). "While the roles of Ankrd52 and Clcn5 in liver disease remain unclear, Peg10 has been widely studied in hepatocellular carcinoma (HCC) pathology." (PMID 31470644, 2019). "PEG10 (Paternally Expressed Gene 10) is not expressed by normal livers but is over-expressed in several human cancers, such as hepatocellular carcinoma (HCC), pancreas cancer, gallbladder cancer, leukemia, breast cancer, and prostate cancer." (PMID 33324350, 2020).
breast carcinoma (6 papers, 2020 to 2024). "PEG10 overexpression has been associated with several malignancies, such as liver cancer, pancreatic cancer and breast cancer 24-26." (PMID 33391523, 2021). "Besides, some studies have demonstrated that OTOR, HOXD3, and PEG10 were associated with prognosis in breast cancer." (PMID 35950033, 2022). "Overexpression of PEG10 in breast cancer cells is mediated by hyperactive status of receptor tyrosine kinases (RTKs), which are driven by external stimuli found within the tumor microenvironment, particularly transforming growth factor, activates RTKs and promotes the signaling cascade." (PMID 38204280, 2024). "Additionally, upregulated expression of PEG10 has been observed in malignancies such as hepatocellular carcinoma, bladder cancer, lung cancer, breast cancer, pancreatic cancer, and cutaneous T-cell lymphoma." (PMID 38017459, 2023). "We also found that knocking out PRKD3 in the breast cancer cells led to the down‐regulation of the c‐MYC target genes such as VEGF, MTA1, PEG10 and hTERT and c‐MYC‐related genes such as CCND, CCNE and E2F." (PMID 31944568, 2020). "We found that the mRNA levels of VEGF, MTA1, PEG10 and hTERT in the PRKD3‐knockout breast cancer cells were lower than the ones in the parental cells." (PMID 31944568, 2020).
endometrial cancer (4 papers, 2021 to 2022). Primary or metastatic malignant neoplasm involving the endometrium (mucous membrane that lines the endometrial cavity). "Also, elevated PEG10 expression has been found in prostate cancer, endometrial cancer, and bladder cancer." (PMID 36385135, 2022).
amyotrophic lateral sclerosis (3 papers, 2023 to 2026). Amyotrophic lateral sclerosis (ALS) is a neurodegenerative disease characterized by progressive muscular paralysis reflecting degeneration of motor neurons in the primary motor cortex, corticospinal tracts, brainstem and spinal cord. "Elevated PEG10 protein expression has been implicated in the neurodegenerative disease Amyotrophic Lateral Sclerosis (ALS) and the neurodevelopmental disease Angelman syndrome." (PMID 39775359, 2024). "PEG10 has also been implicated in another neurological disorder, amyotrophic lateral sclerosis (ALS), a fatal neurodegenerative disease characterized by progressive loss of motor function, typically in middle age." (PMID 37892118, 2023). "PEG10 has also been implicated as the causative gene in Angelman syndrome and amyotrophic lateral sclerosis (ALS)." (PMID 37892118, 2023). "Paternally Expressed Gene 10 (PEG10) is a retroelement-derived human gene that has recently been identified as a putative driver of Amyotrophic Lateral Sclerosis (ALS) and Angelman's Syndrome." (PMID 42239172, 2026).
Angelman syndrome (3 papers, 2023 to 2026). A neurogenetic disorder characterized by severe intellectual deficit and distinct facial dysmorphic features. "In addition to our findings in ALS, PEG10 abundance is also linked to the neurodevelopmental disorder Angelman’s syndrome." (PMID 36951542, 2023).
liver cancer (3 papers, 2017 to 2024). An epithelial or non-epithelial malignant neoplasm that arises from the liver. "We identified the potential role of the m6A-IGF2BPs-PEG10 regulatory axis in liver cancer cells; however, additional research is necessary to clarify the underlying mechanisms." (PMID 39438075, 2024). "PEG10 expression was later shown to be abnormally reactivated in some malignancies (such as liver cancer, lung cancer, and gallbladder cancer) and that it could be a biomarker for progression and prognosis of certain cancers." (PMID 28193232, 2017).
pancreatic cancer (3 papers, 2017 to 2021). "Overexpression of paternally expressed gene-10 (PEG10) is known to promote the progression of several carcinomas, however, its role in pancreatic cancer (PC) is unknown." (PMID 28193232, 2017).
preeclampsia (3 papers, 2017 to 2025). Preeclampsia is a hypertensive disorder of pregnancy that is characterized by new-onset hypertension with proteinuria presenting after 20 weeks of gestation, and depending on mild or severe forms may initially present with severe headache, visual disturbances, and hyperreflexia. "In our study, we identified three trophoblast genes of interest: ANKRD3720 and SERPINA321 which were upregulated and PEG10 which was downregulated in early onset preeclampsia." (PMID 41141914, 2025). "PEG10 mRNA was significantly reduced in placenta from patients with early-onset preeclampsia, relative to controls (P = 0.04)." (PMID 37464405, 2023). "PEG10 mRNA expression was significantly reduced in placentas from patients with early-onset preeclampsia (< 34 weeks’ gestation) relative to controls (p = 0.04, n = 78 vs n = 18 controls)." (PMID 37464405, 2023). "We analyzed the mRNA expression of three imprinting genes SNRPN, PEG10 and MEST in physiological first, second and third trimester groups and placental disorders (preeclampsia and molar pregnancy) and JEG-3 cells (choriocarcinoma cell line)." (PMID 28098215, 2017).
lymph node metastasis (2 papers, 2014 to 2021). "The univariate Kaplan-Meier analysis showed that positive TSG101 and PEG10 expression, and differentiation, tumor size, TNM stage, lymph node metastasis, invasion and surgical curability, is closely associated with a decreased overall survival in SC/ASC and AC patients (P<0.05 or P<0.001)." (PMID 24944680, 2014). "It was demonstrated that positive TSG101 and PEG10 expression were significantly associated with large tumor size, high tumor-node-metastasis (TNM) stage, lymph node metastasis, invasion and no resection (only biopsy) of SC/ASC and AC." (PMID 24944680, 2014).
neuroendocrine tumor (2 papers, 2022 to 2024). "To identify neuroendocrine tumors in our cohort we have added various neuronal markers (i.e., NESTIN, TUBB2B, PEG10) to our gene classifier." (PMID 36230835, 2022).
prostate adenocarcinoma (2 papers, 2021 to 2023). "The placental gene PEG10 (Paternally Expressed 10) is directly repressed by the AR in prostatic adenocarcinoma, and consequently, its expression is significantly elevated in NEPC." (PMID 37761978, 2023). "Yoshie and colleagues found that in prostate adenocarcinoma (PACA) patients, overexpression of PEG10 is linked to a reduction in PACA patient survival." (PMID 33962392, 2021).
chondrosarcoma (1 paper, 2017). A malignant cartilaginous matrix-producing mesenchymal neoplasm arising from the bone and soft tissue. "Induction of Peg10 mildly but significantly inhibited the activity of TGF-β-SMAD2/3-responsive 9xCAGA luc in not only C28/I2 chondrocytes but also chondrosarcoma cell lines." (PMID 29044189, 2017). "Our results indicate that mutually exclusive expression of PEG10 and phosphorylated SMADs in combination with differentially expressed SOX9 is an index to distinguish between enchondroma and chondrosarcoma, while PEG10 and TGF-β signalling are mutually inhibitory in chondrosarcoma cells." (PMID 29044189, 2017).
depression (1 paper, 2016). "The decreased expressions of mRNAs in CUMS-induced depression mice include Slc6a11, Hap1, Gad1, Gad2, Gng4, Slc32a1, Doc2g, Slc32a1, Magel2, Prkcd, Ngfr, Dusp1, Th, Itih3, Cacna2d2, Arc, Mbp, Peg10, Fos, and so on." (PMID 27427907, 2016).
ductal carcinoma in situ (1 paper, 2009). "PEG10 is a c-Myc target gene in cancer cells and has been shown to be activated during breast tumorigenesis, expressed in 55% of ductal carcinoma in situ and 32% of invasive ductal carcinoma." (PMID 19671193, 2009).
embryonal carcinoma (1 paper, 2016). A non-seminomatous malignant germ cell tumor characterized by the presence of large germ cells with abundant cytoplasm resembling epithelial cells, geographic necrosis, high mitotic activity, and pseudoglandular and pseudopapillary structures formation. "Two major gene families are derived from Ty3/Gypsy long terminal repeat (LTR) retrotransposons, PEG10 (Human Paternal Expression Gene 10, also known as EDR, embryonal carcinoma differentiation regulated) being in one of the families and PNMA related genes in the other." (PMID 27436286, 2016).
ovarian carcinoma (1 paper, 2022). A malignant neoplasm originating from the surface ovarian epithelium. "PEG10 is expressed mainly in the placenta, and has already been identified as a gene highly associated with ovarian cancer stem cells." (PMID 35892844, 2022). "We found that PEG10 and SLC3A1 are the marker genes of cancer cells in the earliest stage or cancer stem-like cells in ovarian cancer; C0, one of the two malignant tumor clusters, includes these cancer stem-like cells." (PMID 35892844, 2022).
rectal adenocarcinoma (1 paper, 2021). "PEG10 is one of the upregulated genes in the tissues of rectal adenocarcinoma with metastasis when compared to corresponding tumor tissues without metastasis." (PMID 33506057, 2021).
steatosis (1 paper, 2020). Increased lipid within the cytoplasm of cells. "Of the top-ranked 10 genes, two genes (CYP7A1 and PEG10) were significantly up-regulated in both steatosis and NASH patients, while eight genes (FOSB, FOS, IL6, GADD45G, MYC, SLITRK3, JUNB, and IGFBP2) were significantly down-regulated." (PMID 33324350, 2020).
tumor (26 papers, 2008 to 2025). "Among these significant genes of IL-4 signaling are CFLAR, ALOX5, PMAIP1, EGR1, NCF2, SLC39A8, and PEG10 which have been reported to be associated with tumor progression or chemotherapy-drug resistance through effecting proliferation and apoptosis in previous studies." (PMID 33506057, 2021). "A somatic example of Peg10 loss-of-imprinting has been found in several tumor types." (PMID 18958286, 2008). "PEG10 (paternally expressed gene 10) promotes tumor invasion and metastasis, and is a major regulator in TGFB1-induced EMT." (PMID 36980828, 2023). "With the development of embryo, the expression of PEG10 was lessened but ascended in the tumour, thus highlighting its important role in the early period of embryo to tumour." (PMID 34775482, 2021). "As expected, overexpression of WT Nf1 in KPΔNF1 cells downregulates Fak1, downregulates its target genes Psat1, Areg, and Peg10, retards tumor growth, and rescues cytotoxicity induced by CB‐839 or AOA." (PMID 31036704, 2019). "Similarly, the expression of TSG101 and PEG10 in HCC tissues were significantly increased compared with the non‐tumour tissues, which was in line with our results found above." (PMID 30450735, 2019). "In addition, we assessed the expression and distribution of TSG101 and PEG10 in non‐tumour tissues and HCC patients by immunohistochemistry." (PMID 30450735, 2019). "Among the top 100 deregulated genes, Wnt-associated genes such as LGR5, DKK1, and NKD1, as well as the HB-related genes DUSP9, DLK1, PEG3, PEG10, IGF2BP1, and IGF2BP2 were consistently upregulated in tumor samples." (PMID 40968384, 2025). "Given their hyperactivation-promoting tumor abilities, the hsa-miR-1225-5p interaction targets LASP1, PEG10, and MYC that were chosen from curated open data have been thoroughly examined in tumor models with meaningful participation." (PMID 38204280, 2024). "Previous studies have revealed that SNAI3-AS1 is upregulated in HCC, and can promote tumor cell proliferation and metastasis by activating UPF1/Smad7 signaling pathway and by acting as a sponge for miR-27-3p and miR-34a-5p to upregulate PEG10." (PMID 37202791, 2023). "We further established an MS-based immunopeptidomic approach for identifying tumor-specific antigens from the placenta and identified GPC3 and PEG10 as HCC antigens with high immunogenicity recognized by T cells." (PMID 37932427, 2023). "Based on TCGA normal and GTEx database, the expressions of these genes in PC were analyzed, and the levels of PEG10, TFAP2A and EGR3 was remarkably greater in tumor compared to normal group (P <0.01)." (PMID 36284637, 2022). "When taking into account the different tumour subtypes, we detected 24 SNPs (in eight genes: ZDBF2, PEG10, MEST, H19, IGF2, MEG3, ZNF331 and HM13) exhibiting DI in at least one subtype compared to the normal tissue samples." (PMID 30297886, 2018). "Cox’s multivariate analysis demonstrated that differentiation, tumor size (≥3 cm), TNM stage, lymph node metastasis, invasion, surgical procedure and TSG101- and PEG10-positive expression positively correlated with the poor survival rate of the AC patients." (PMID 24944680, 2014). "The following DMRs showed aberrant methylation in only one tumor: ARH1-CG1, NAP1L5-DMR, PEG10-DMR, H19 promoter, WT1-AS-DMR, MEG3-CG7-DMR, MCTS2-DMR, NESP-DMR, and GNAS1A-DMR." (PMID 24373183, 2013). "Among them were known cancer/testis antigen genes (PNMA5, SPATA22, ROR1, and CT45A6) and some new candidates (PAX2, HES4, PEG10, NTN4, PDE10A, and POSTN), these genes could be useful tumor markers and potential therapeutic targets." (PMID 30922328, 2019).
cancer (25 papers, 2009 to 2024). A tumor composed of atypical neoplastic, often pleomorphic cells that invade other tissues. "Recent findings have discovered novel oncogenes on chromosome 7 (e.g., GTF2IRD1 and PEG10) associated with progression in other cancer types." (PMID 34885165, 2021). "PEG10, a paternally expressed imprinted gene that encodes a cytosolic protein, is primarily expressed in the placenta, and its expression levels are elevated in a variety of cancers, including in HCC." (PMID 37932427, 2023). "In our study, PEG10 was a marker gene of S3, which was mainly expressed in embryo and malignant tumour." (PMID 34775482, 2021). "Peg10 is a known oncogene and has been shown to interact with Nanog and Oct4 in human cancer cells, and Larp1 is thought to regulate translation downstream of the mTor pathway." (PMID 33863351, 2021). "The genes MACC1, PEG10, CALCOCO1, and MEF2C have been found to be implicated in cancer." (PMID 24086395, 2013). "Additionally, we identified SLC3A1 and PEG10 as the marker genes of the earliest cancer cells." (PMID 35892844, 2022). "By analyzing scRNA-seq data from 486 cancer cells across subtypes, we identified multiple SNPs in imprinted genes, including HM13, MEST (PEG1), SNHG14 and PEG10, showing consistent biallelic expression." (PMID 39766305, 2024). "After examining the pulled‐down proteins by lncRNA ARHGAP5‐AS1 using mass spectrometry proteomics, we identified multiple cancer‐related proteins including CSDE1, ZC3HAV1, CCT8, CKAP4, PARP1, PEG10 and APEX1 in HepG2." (PMID 36354136, 2022). "Although the overexpression of PEG10 and TSG101 in cancer cells has been previously studied, their expression in SC/ASC and AC of the gallbladder has yet to be identified." (PMID 24944680, 2014). "Some genes, which appeared to be virtually switched off in B4GALNT2-expressing cells, are involved in the basic properties of cancer cells, such as stemness (SOX2, ROR1), epithelial to mesenchymal transition (EMT) (NID1, ALX1), and growth (FAM110B, PEG10, MID2)." (PMID 32290493, 2020).
neurological disease (1 paper, 2024). "PEG10 is a retroelement-derived Mart-family gene that is necessary for placentation and has been implicated in neurological disease." (PMID 39775359, 2024).
PEG10 also shares sentences with these, for which no sentence is quoted: B-cell lymphocytic leukemia (3 papers); prostate carcinoma (3); adenocarcinoma of the gallbladder (2); gallbladder cancer (2); leukemia (2); lung carcinoma (2); Miscarriage (2); peritonitis (2); acute lymphoid leukemia (1); adenosquamous carcinoma (1); allergic conjunctivitis (1); asthma (1); bladder cancer (1); Cardiovascular Diseases (1); chronic heart failure (1); cirrhosis of the liver (1); colitis (1); COVID-19 (1); diabetic nephropathy (1); gastric cancer (1); infection (1); invasive ductal carcinoma (1); liver disease (1); malignant pheochromocytomas (1); myocardial infarction (1); neurodegenerative disease (1); neurodevelopmental disorder (1); oral squamous cell carcinoma (1); placental disorders (1); prostate tumours (1).
A further 3 diseases each share a sentence with PEG10 in 1 paper.